PKD1 (polycystin 1, transient receptor potential channel interacting)
Diseases named in the same sentence as PKD1 in open-access papers (continued):
Sharing a sentence is not in itself a finding about the gene and the disease.
polycystic kidney disease (continued). "The gene responsible for the 85% of the cases is the polycystic kidney disease 1 PKD1 gene located on the shorter arm of the 16th chromosome, and the other gene responsible for the rest of the cases is the polycystic kidney disease 2 PKD2 gene located on the longer arm of the 4th chromosome." (PMID 23840219, 2013). "Mutations in PKD1 and PKD2 genes are responsible for the development of polycystic kidney disease." (PMID 23997766, 2013). "We have utilized this vector system to rapidly design, construct and validate multiple de novo HACs containing large (100–200 kb) genomic loci including therapeutically significant genes for human growth hormone (HGH), polycystic kidney disease (PKD1) and ß-globin." (PMID 15998466, 2005). "The most common VUS overall were not KSD-linked, including polycystic kidney disease (PKD1, N = 21), familial Mediterranean fever (MEFV, N = 17), Fraser syndrome (FRAS1, N = 11), familial hyperaldosteronism type IV (CACNA1H), and Senior-Loken syndrome 4 (NPHP4, N = 10)." (PMID 40126616, 2025). "The causes of atypical polycystic kidney disease by imaging are heterogeneous and may include somatic mosaicism, mild disease associated with PKD1 non-truncating or PKD2 mutations, as well as mutations in other cystic disease genes." (PMID 36807559, 2023). "However, the major genes involved in polycystic kidney and liver diseases such as PKD1, KD2, SEC." (PMID 29555974, 2018). "To test if this technique could be applied to evaluate disease gene transcripts present in urine pellets, we examined the large polycystic kidney disease gene PKD1 transcript by MLPA and long-range PCR and found that it was readily detectable in urine pellet DNA." (PMID 26577187, 2015). "Thus, the deletion of exon 30 is associated with altered renal function but not with mutation in PKD1 or polycystic kidney disease status." (PMID 24358217, 2013). "We identified five homologs of polycystic kidney disease (PKD): PKD1-1, PKD1-2, PKD1-3, PKD1-4, and, PKD2, from the P. naikaiensis genome." (PMID 38305882, 2024). "Deletions larger than 2000 kb including the PKD1 and TSC2 genes lead to severe MR with polycystic kidney disease and tuberous sclerosis, respectively." (PMID 32005695, 2020). "In addition, PKD1 gene mutations in this group of patients are located on chromosome 16, so far, there is no report on whether the mutation of PKD1 gene in addition to chromosome 15 will also cause polycystic kidney disease in MFS patients." (PMID 33200202, 2020). "Molecular analysis has revealed that, in the majority of cases of severe polycystic kidney disease observed in TSC, large deletions of chromosome 16 affecting both the TSC2 and the PKD1 gene can be observed." (PMID 19863783, 2009). "Contiguous gene deletion syndrome, characterized by both TSC and polycystic kidney disease, affects up to 5% of TSC patients and has been diagnosed in the two patients with TSC2 segmental deletions encompassing PKD1 exon 46, assisted in a multispecialty clinic." (PMID 39596632, 2024). "In addition, miR-17 has been shown to downregulate polycystin-1 (PKD1) and polycystin-2 (PKD2), crucial for the mechanosensory function of primary cilia in polycystic kidney disease." (PMID 39268086, 2024). "To detect PC1-p30 in vivo, we used the Balb/c polycystic kidney (bpk) mouse model, a nonorthologous model for early-onset PKD in which the Pkd1 alleles are unaffected." (PMID 37579949, 2023). "The effect of preprocessing on radiomic features was investigated using a single T2-weighted fat saturated (T2W-FS) MRI scan from PKD1 and PKD2 subjects (29 kidneys in total) from the Consortium for Radiologic Imaging Studies of Polycystic Kidney Disease study." (PMID 38156331, 2023). "The PKD1 gene is proximal tothe TSC2 gene on chromosome 16, and may lead to the possibility ofTSC/PKD contiguous gene syndrome and the development of polycystic kidney disease(PKD)." (PMID 35638823, 2022).
polycystic kidney disease (continued). "NGS did not detect clear pathogenic mutations related to the polycystic kidney phenotype, yet MLPA results indicated a heterozygous deletion mutation in exon 18 of the PKD1 gene (PKD1-18 nt–290 nt)." (PMID 36699011, 2022). "We detected enhanced renal cyst growth and cell proliferation in male mice lacking expression of the polycystic kidney disease gene Pkd1 (polcycystin 1), when compared to female Pkd1−/− mice." (PMID 34199520, 2021). "In conclusion, the oral administration of trehalose in Pkd1 miR Tg mice did not ameliorate the progression of polycystic kidney disease." (PMID 30585217, 2018). "As p.Pro123Ala was predicted to be a disease-causing mutation by three tools and p.Ile764Met was predicted to be benign by PolyPhen-2, the possibility that p.Leu727Pro in PKD1 and p.Pro123Ala in GANAB co-contribute to the development of polycystic kidney with liver disease cannot be excluded." (PMID 30333007, 2018). "For polycystic kidney disease, the testing approach should be able to detect copy-number variations (CNVs) such as heterozygous deletions (e.g., in HNF1B) and to cover even complex genomic regions such as the PKD1 gene." (PMID 29479522, 2017). "The biological functions of C-terminal two putative polycystic kidney disease domains (PKD1 and PKD2) has not yet been fully investigated, although they have been suggested to be involved in protein-protein or protein-carbohydrate interaction." (PMID 26222047, 2015). "Homozygous Pkd1 null mice appear normal when born, but rapidly develop polycystic kidneys and generally do not live longer than 3.5 to 4 weeks." (PMID 19099603, 2008). "At the age of 51 years, several kidney cysts were detected, raising the suspicion of polycystic kidney disease, which was later excluded by next-generation sequencing genetic testing: negative for Polycystin 1 (PKD1), Polycystin 2 (PKD2), and Ciliary IPT domain-containing fibrocystin (PKHD1) genes." (PMID 40130200, 2025). "To determine whether the changes in Glis2 expression found in Pkd1 models are extensible to other preclinical models of ADPKD, we used a mouse model in which polycystic kidney disease resulting from inactivation of Pkd2 is rapidly reversed by re-expression of Pkd236." (PMID 38693102, 2024). "Pathogenic PKD1 variants have previously been reported in SCAD patients, and the observation here highlights that the co-occurrence of SCAD and PKD1 dysfunction is moving beyond being merely anecdotal, although notably, not every SCAD patient with PKD1 variants had polycystic kidneys." (PMID 33125268, 2020). "In conclusion, the conditional deletion of Pkd1 from mesenchymal lineage results in both defective bone formation and polycystic kidney and pancreatic but not liver disease, indicating that val function in mesenchymal precursors to regulate skeletal, renal, and pancreatic development." (PMID 23029375, 2012). "In addition, neither single Pkd1 and Kif3a nor double Pkd1 and Kif3a mutant mice developed polycystic kidney disease, unlike the reported additive effects of Pkd1 and Pkd2 deficiency to enhance renal cyst formation." (PMID 21151991, 2010).
Renal cyst (169 papers, 2007 to 2026). A fluid filled sac in the kidney. "In this study, we report a case of a boy presenting with microscopic hematuria with multiple renal cysts and carrying an unreported intronic variant, c.12445-34_12445-10del, in the PKD1 gene inherited from his father who also presented PKD." (PMID 41659037, 2026). "In Bull Terriers, it is known to result from a pathogenic mutation in the PKD1 gene, and multiple renal cysts can be identified by ultrasonography." (PMID 40723533, 2025). "Mice homozygous for Pkd1-null alleles initiate renal cysts from E15.5, but perinatal lethality complicates use for pharmacologic studies." (PMID 41122971, 2025). "Despite a low-frequency mosaic splicing PKD1 variant, he developed severe renal cysts and end-stage renal disease in his 30 s." (PMID 38548773, 2024). "In ADPKD, signaling pathways activated in renal cysts by loss of PKD1 include many known to be activated and growth-promoting in cancer including WNT/CTNNB1, PI3K/AKT, mTOR/S6K, RAF/MEK/ERK, SRC, MYC, AURKA, and others." (PMID 37542051, 2023). "Studies have shown that some but not all compounds associated with the activation of AMPK attenuate cystic kidney disease in Pkd1 mutant animal models." (PMID 36743216, 2023). "This is mainly because the miR-17∼92 cluster targets and inhibits genes associated with cystic kidney diseases, including polycystin 1/2 (Pkd1/2) and HNF-1β." (PMID 37680850, 2023). "Noncanonical activation of TFEB is characteristic of cystic epithelia in multiple models of renal cystic disease including those associated with loss of Pkd1." (PMID 36794754, 2023). "According to this concept, the etiology of ADPKD involves a heterozygously inherited mutation and somatic mutation in the other normal PKD1 allele, resulting in the complete loss of function of PKD1, ultimately leading to renal cyst formation." (PMID 34980882, 2022). "In a rescue experiment, overexpressing human Pkd1 prevented embryonic lethality in Pkd1−/− mice but caused cystic kidney disease in Pkd1+/+ animals." (PMID 35253003, 2022). "Subsequent models confirmed that Pkd1 overexpression and, to a lesser extent, Pkd2 cause cystic kidney disease." (PMID 35253003, 2022). "Renal cysts mostly develop due to mutations in PKD1 (ca. 78%) or PKD2 (ca. 15%), encoding for polycystin 1 (PC1) and 2 (PC2), respectively." (PMID 34948309, 2021). "The years 1995 and 1996 marked the discovery of Polycystin 1 (PKD1) and Polycystin 1 (PKD2) as the first genes to be associated with cystic kidney disease through positional cloning." (PMID 34828368, 2021). "Four of these—coding variants in GCK with diabetes mellitus, LoF variants in HBB with hemoglobinopathies, LoF variants in PKD1 with cystic kidney disease, and coding variants in MIP with cataracts—are novel conditions for population screening." (PMID 34385667, 2021). "The mutations of PKD-1 and the downregulation of PC-1 have been proved to be associated with renal cyst formation, as well as abnormal epithelial cell proliferation, cell adhesion and cell-matrix communication." (PMID 33071810, 2020). "A recent study showed co-occurrence of hepatic and renal cysts was found in 20 (12.6%) out of 159 cat cases with renal cyst(s), and all cases were positive for the PKD1 mutation." (PMID 31299928, 2019). "We used renal cyst epithelial cells (CRC) isolated from patients with ADPKD (carrying a PKD1 mutation) from the Genkyst cohort who had undergone nephrectomy." (PMID 29986647, 2018). "Among the 28 family members, the 12 individuals that carried the PKD1 mutation (p.Q2243X) showed typical ADPKD manifestations including renal cysts, and renal enlargement in all but the one case where the data was unavailable." (PMID 25880449, 2015). "In this system, the loss of Pkd1 at post-natal day 28 results in development of renal cysts at ~4.5–5 months of age, progressing to severe enlargement of the kidney and renal failure at 6–7 months of age." (PMID 26528438, 2015).
Renal cyst (continued). "In global knockout mice it is difficult to differentiate between indirect extra-renal abnormalities due to the effects of the complex metabolic alterations caused by renal cystic disease from direct effects caused by loss of Pkd1 functions in affected tissues." (PMID 23029375, 2012). "Consistent with a two-hit mechanism, mice that are homozygous for inactivating mutations of either Pkd1 or Pkd2 develop cystic kidneys, edema and hemorrhage and typically die in midgestation." (PMID 20862291, 2010). "Pkd1 and Pkd2 heterozygous mice present with few if any renal cysts but develop dramatic cystic disease when the other allele undergoes somatic deletion at a high rate." (PMID 20862291, 2010). "ADPKD is primarily caused by mutations in the PKD1 (80%) or PKD2 (20%) genes, which generate a mutated protein product called polycystin 1, a mechanoreceptor in the cilium, leading to the formation of renal cysts and, frequently, extrarenal manifestations such as hepatic cysts." (PMID 41283517, 2025). "However, to our knowledge, our work is the first to demonstrate a molecular consequence of a Pkd1 mutation on the microvasculature within cystic kidneys." (PMID 40114603, 2025). "While the effects on ANKMY2 loss on mature glycoslylated levels of adenylyl cyclases contributes to lack in plasma membrane localization, such reduction was not sufficient to circumvent later changes in adenylyl cyclase/cAMP signaling in cystic kidneys from Pkd1 loss." (PMID 41474822, 2025). "Thus, renal cyst formation in this mouse model by 3-month old should be caused by the cystic cell EVs/exosome treatment that induced the downregulation of Pkd1." (PMID 34315885, 2021). "The results of the present study may be summarized as follows: (i) Renal cysts found in ADPKD caused by knockout of Pkd1, are associated with enhanced basal intracellular Ca2+ levels and enhanced agonist (ATP)− and CPA-induced Ca2+ store release and SOCE." (PMID 34199520, 2021). "This hypothesis is supported by experiments in Pkd1 heterozygous mice which develop more severe renal cystic disease after ischemia reperfusion injury, suggesting that PKD1 mutations increase the hypoxia sensitivity of the kidney." (PMID 33255651, 2020). "Hartman found that Rapamycin enhanced cilia formation in TSC1 and TSC2 null cells and concluded that the efficacy of mTOR inhibitors on renal cystic disease in patients carrying a TSC mutation or PKD1/TSC2-CGS may differ from its efficacy in ADPKD." (PMID 26077033, 2015). "For example, mutations in Pkd1 cause a more severe cystic kidney phenotype than mutations in Pkd2." (PMID 25464512, 2014). "Consequently, when a variant is identified in a collagen gene in a patient with cystic kidney features, a comprehensive evaluation for concurrent variants in PKD1, PKD2, or other cystic kidney disease-associated genes might not be routinely performed." (PMID 40565535, 2025). "Moreover, we also detected PKD1 compound mutations, which may explain that the patient P1 had early disease onset at the age of five and large renal cysts (38 mm)." (PMID 34868264, 2021). "Given that p68 is involved in the regulation of Pkd1 gene expression and signaling pathways associated with cystic renal epithelial cell proliferation and renal fibrosis, we are wondering whether p68 plays a critical role in renal cyst formation." (PMID 32724471, 2020). "We examined independent ADPKD cell lines derived from cystic kidney epithelia isolated from nephrectomy specimens of three individuals with ADPKD, and each carrying a distinct pathogenic monoallelic PKD1 mutation." (PMID 41558825, 2026). "Two other mutations, PKD1 and PKD2, are associated with CKD and cystic kidney disease, respectively, and map to polycystin 1 and polycystin 2, respectively." (PMID 41511357, 2026). "Renal Kcnn4 upregulation in all tested Pkd1 mouse models of ADPKD suggests that Kcnn4 plausibly contributes to renal cyst growth in ADPKD." (PMID 41122971, 2025).
Renal cyst (continued). "To assess Kcnn4 spatial expression in cystic kidneys, we examined early- and adult-onset Pkd1 mouse models of ADPKD by RNAScope." (PMID 41122971, 2025). "A previous study showed that miR-192-5p, miR-194-5p, miR-30a-5p, miR-30d-5p, and miR-30e-5p were significantly downregulated in the urinary exosomes of patients, murine PKD1 cystic kidneys, and human PKD1 cystic kidney tissues." (PMID 40308771, 2025). "Once-daily oral senicapoc treatment of the 2 more slowly progressive Pkd1 mouse models for 12 wk markedly attenuated renal cyst growth and number, reduced fibrosis, and slowed deterioration of renal function." (PMID 41122971, 2025). "The occurrence of renal cysts in patients with COL4A3-COL4A5 variants, independently of PKD1 or PKD2 alterations, underscores the broader implications of collagen IV defects in cystogenesis." (PMID 40565535, 2025). "Although the phenomenology of PKD1 and PKD2 mutations is identical, PKD2 patients experience less severe disease, a less early development of hypertension and atherosclerosis, and probably fewer renal cysts compared to PKD1 patients." (PMID 40362206, 2025). "The amounts of phosphorylated and total ERK in whole kidney lysates increased in Pkd1 cko cystic kidneys compared to Dko kidneys." (PMID 41474822, 2025). "Levels of Kim1 transcripts significantly increased in Pkd1 cko cystic kidneys compared to Dko kidneys and remained unchanged in Pax8rtTA; TetO-Cre; Ankmy2f/f kidneys compared to controls." (PMID 41474822, 2025). "Several Pkd1 mouse models exhibiting widely differing rates of bilateral renal cyst growth and disease progression can serve to study pathogenesis and test therapeutic approaches." (PMID 41122971, 2025). "Upregulation of KCNN4 expression in human ADPKD kidneys, as well as in kidneys of several mechanistically distinct Pkd1 mutant mouse models, is consistent with a role of KCa3.1 in cystic kidney disease." (PMID 41122971, 2025). "Over the course of this study, P18 iKsp-Pkd1del mice developed highly cystic kidneys which were on average 7-fold the normalised weight of Pkd1 wildtype mouse kidneys." (PMID 38846086, 2024). "Here we performed the complementary analysis of gene sets that were downregulated in PKD1 renal cysts, the majority (77/84) of which were found to be involved in metabolic reprogramming." (PMID 39000280, 2024). "In conclusion, the present analysis highlights a complex rewiring of energy metabolism in human PKD1 renal cysts at the level of gene expression." (PMID 39000280, 2024). "We found gene expression profiles of PKD1 renal cysts were consistent with the Warburg effect with gene pathway changes favoring increased cellular glucose uptake and lactate production, instead of pyruvate oxidation." (PMID 39000280, 2024). "Our pathway analysis revealed that GSH metabolism, as well as drug metabolism via multiple enzymes, including cytochrome P450, were all downregulated in human PKD1 renal cysts." (PMID 39000280, 2024). "Taken together, these results suggest that, instead of fully oxidizing glucose, the PKD1 renal cysts shuttle glucose through aerobic glycolysis and the PPP in order to sustain cell growth and proliferation." (PMID 39000280, 2024). "The youngest two patients (1 month and 6 months, respectively) had renal cysts detected intrauterine that underwent genetic testing in the first 6 months after birth with the PKD1 gene identified." (PMID 38790570, 2024). "KEGG pathway analysis identified glycolysis/gluconeogenesis, pentose phosphate pathway (PPP), and pyruvate metabolism as downregulated in human PKD1 renal cysts." (PMID 39000280, 2024). "For instance, miR-30a-5p, miR-30d-5p, miR-30e-5p, miR-192-5p, and miR-194-5p exhibited notable downregulation in patients’ exosomes, murine Pkd1 cystic kidneys, and human PKD1 cystic kidney tissue." (PMID 38275604, 2024). "Taken together, these results suggest aberrant GSH synthesis and GSH-dependent antioxidant response in PKD1 renal cysts." (PMID 39000280, 2024).